USP18 (ubiquitin specific peptidase 18)
Description:
Interferon-induced ISG15-specific protease that plays a crucial role for maintaining a proper balance of ISG15-conjugated proteins in cells. Regulates protein ISGylation by efficiently cleaving ISG15 conjugates linked via isopeptide bonds. Regulates T-cell activation and T-helper 17 (Th17) cell differentiation by deubiquitinating TAK1, likely to keep TAK1-TAB complexes in steady conditions. In turn, restricts activation of NF-kappa-B, NFAT, and JNK as well as expression of IL2 in T-cells after TCR activation. Acts as a molecular adapter with USP20 to promote innate antiviral response through deubiquitinating STING1. Involved also in the negative regulation of the inflammatory response triggered by type I interferon. Upon recruitment by STAT2 to the type I interferon receptor subunit IFNAR2 interferes with the assembly of the ternary interferon-IFNAR1-IFNAR2 complex and acts as a negative regulator of the type I interferon signaling pathway. [Isoform 2]: Has enzymatic activity similar to isoform 1 and interferes with type I interferon signaling. Major deISGylation enzyme for nuclear proteins.
Synonyms: ISG43; PTORCH2; UBP43
Tractability: PROTAC: ubiquitination databases record sites on it.
Target class: Cysteine protease; Cysteine protease CA clan; Protease; Enzyme; Cysteine protease C19 family
Gene: Protein-coding gene on chromosome 22 (18,148,399 to 18,177,397, forward strand). Ensembl gene ENSG00000184979.
Subcellular location: Cytoplasm (Isoform 1); Nucleus (Isoform 2); Cytoplasm
Subcellular location (Human Protein Atlas): Cytosol; Vesicles
Pathways (Reactome):
Immune System: ISG15 antiviral mechanism; Regulation of IFNA/IFNB signaling; Regulation of NF-kappa B signaling; TAK1-dependent IKK and NF-kappa-B activation
Metabolism of proteins: Ub-specific processing proteases
Gene Ontology:
Molecular function: cysteine-type deubiquitinase activity; ISG15-specific peptidase activity; molecular adaptor activity; protein binding
Biological process: antiviral innate immune response; negative regulation of cGAS/STING signaling pathway; negative regulation of ferroptosis; negative regulation of type I interferon-mediated signaling pathway; protein deubiquitination; regulation of inflammatory response; response to other organism; response to stilbenoid
Cellular component: cytoplasm; cytosol; nucleus
Genetic constraint (gnomAD): Loss-of-function variants: 11 observed, 39.69 expected, observed/expected ratio (o/e) 0.28, 90% interval 0.17 to 0.46. The upper end of that interval is the gene's LOEUF score, 0.46, which puts it in group 2 of 6, group 1 being the genes least tolerant of losing a copy. Missense variants: 280 observed, 385.32 expected, observed/expected ratio (o/e) 0.73, 90% interval 0.66 to 0.8. Synonymous variants: 112 observed, 141.92 expected, observed/expected ratio (o/e) 0.79, 90% interval 0.68 to 0.92.
Homologues: Orthologues: chimpanzee USP18 (99% identical), macaque USP18 (93% identical), rabbit USP18 (77% identical), dog USP18 (76% identical), mouse Usp18 (70% identical), rat Usp18 (70% identical), pig USP18 (66% identical). Paralogues in human: USP15 (26% identical), USP4 (26% identical), USP32 (25% identical), USP24 (24% identical), USP33 (24% identical), USP6 (24% identical), USP19 (24% identical), USP11 (23% identical), USP9X (23% identical), USP47 (23% identical), USP37 (23% identical), USP2 (22% identical), and 59 more.
Diseases named in the same sentence as USP18 in open-access papers:
USP18 is named in the same sentence as 153 diseases in open-access papers, as found by Europe PMC text mining. Sharing a sentence is not in itself a finding about the gene and the disease. The quoted sentences say what the papers report.
viral infection (42 papers, 2012 to 2026). "ISG15‐deficient cells exhibited enhanced and prolonged ISG expression and a concomitant resistance to virus infection, a phenotype also associated with USP18 deficiency." (PMID 39931755, 2025). "The JAK–STAT pathway is activated and prolonged in USP18−/− cells following interferon stimulation leading to increased production of ISGs and greater resistance to cytopathic effects caused by a number of viral infections." (PMID 37756534, 2023). "More specifically, the ubiquitin specific peptidase 18 (USP18) gene, which is associated with innate immunity to viral infection is a potential candidate gene located in this region on SSC5." (PMID 34875996, 2021). "We observed that MAVS of Usp18−/− MEF displayed significantly less K63-linked polyubiquitination following viral infection compared with that of Usp18+/+ MEFs." (PMID 34016972, 2021). "Third, immunoprecipitation followed by probing with K63-Ub specific antibody or TUBE assay against K63-specific linkages further strengthened the observation that deficiency of USP18 led to the decrease of K63-linked polyubiquitination of MAVS during viral infection." (PMID 34016972, 2021). "Mice with a deficiency of USP18 are more susceptible to viral infection." (PMID 34016972, 2021). "Consistently, Usp18−/− mice were more susceptible to viral infection compared with wild-type mice." (PMID 34016972, 2021). "Thus, our work pointed out that the role of USP18 in innate immunity and in particular in a cell's susceptibility and response to viral infection is considerably more complex than previously thought although the precise mechanism for this effect remains to be investigated." (PMID 31871427, 2019). "As ISGylation pathway plays an important role in antiviral immunity as a defense mechanism, it would be of great interest to investigate USP18 inhibitors in viral infections." (PMID 39843430, 2025). "To investigate the role of USP18 in the regulation of the viral infection, we measure the SeV viral protein using the SeV antibody in MEF cells after infection with SeV." (PMID 34016972, 2021). "As expected, overexpression of USP18 caused the formation of more MAVS aggregates, while the deletion of USP18 negatively regulated the aggregation of MAVS upon viral infection." (PMID 34016972, 2021). "We observed that the interaction between MAVS and TRIM31 following viral infection was significantly impaired in Usp18−/− MEFs compared with Usp18+/+ MEFs." (PMID 34016972, 2021). "Upon viral infection, USP18 is critical for the re-localization of TRIM31 from the cytoplasm to mitochondria and the interaction between TRIM31 and MAVS." (PMID 34016972, 2021). "Elucidation for the role of USP18 in immune responses against viral infection is far more complicated, even though the importance of USP18 has become enormously pinpointed." (PMID 32957626, 2020). "Further studies investigating the effects of USP18 on other viral infections should be done to reveal its potentiality as a biomarker of diseases and as a therapeutic target." (PMID 31871427, 2019). "The roles of the USP18 pathway in viral infection differ depending on the virus involved and can be mediated through multiple different routes." (PMID 31871427, 2019). "The finding that hepatic USP18 expression is modulated by inflammatory stimuli is a new paradigm for the interaction of the liver inflammatory microenvironment and viral infection." (PMID 27009955, 2016). "The mechanisms controlling USP18 expression in the liver are poorly understood but will have relevance to understanding innate immune mechanisms in chronic viral infection." (PMID 27009955, 2016). "Only virus infection, supported by the Usp18 driven enforced virus replication process in CD11c+ APCs is efficient in breaking immunologic tolerance to pancreatic islet cells in our model." (PMID 24204252, 2013).
viral infection (continued). "Covalent linkage of the ubiquitin-like protein ISG15 interferes with viral infection and USP18 is the major protease which specifically removes ISG15 from target proteins." (PMID 22916876, 2012). "Usp18 is induced by viral infection and type I interferons and inhibits apoptosis." (PMID 39184324, 2024). "Absence of USP18 leads to increased resistance to viral infections, some of which can be recapitulated by loss of enzymatic activity." (PMID 37756534, 2023). "Surprisingly, humans with ISG15 deficiency do not show increased susceptibility to viral infection, possibly due to concomitant reduction of USP18 expression and USP18-dependent negative regulation of IFN-dependent signaling." (PMID 37025175, 2023). "USP18 can also be induced by lipopolysaccharide (LPS) stimulation or virus infection." (PMID 34017322, 2021). "Following viral infection, USP18 is enriched in mitochondria and promotes the mitochondrial translocation of TRIM31 from the cytoplasm and interaction between TRIM31 and MAVS, consequently enhancing TRIM31-mediated K63-linked polyubiquitination and subsequent aggregation of MAVS." (PMID 34016972, 2021). "Consequently, deletion of USP18 in macrophages or fibroblasts leads to impaired type-I interferon response following viral infection." (PMID 34016972, 2021). "More recent evidence has reported the role of USP18 in innate defense to virus infection." (PMID 34017322, 2021). "More importantly, USP18 is enriched in the mitochondrial fraction following the viral infection." (PMID 34016972, 2021). "It has been shown that USP18-deficient mice show IFN hypersensitivity and significant resistance to the cytopathic effects of vesicular stomatitis virus (VSV), lymphocytic choriomeningitis virus (LCMV) and sindbis virus (SINV), indicating the role of USP18 in innate immunity against viral infection." (PMID 32957626, 2020). "These diverse effects on virus infections implicate that USP18 functions via virus-specific and/or species-specific fashions which may be mediated by the interaction of USP18 and certain viral proteins." (PMID 32248821, 2020). "In addition, USP18C61A/C61A mice show increased resistance to infection with vaccinia and influenza B virus as well as against Coxsackie b virus induced myocarditis highlighting the importance of the protease function of USP18 in viral infections." (PMID 30126853, 2018). "Though the underlying mechanism of increased USP18 is currently unclear, this may provide a useful model to further probe the biological roles of USP18 in viral infection." (PMID 27227879, 2016). "During acute viral infection, viral replication in secondary lymphatic organs is essential for activating the innate and adaptive immune responses, and the replication is dependent on USP18." (PMID 27227879, 2016). "Additionally, USP18 is remarkably induced after viral infection." (PMID 34017322, 2021). "Thus, inhibiting USP18 catalytic activity might represent a novel strategy to counteract viral infection." (PMID 30126853, 2018). "Here we showed that the ability of ISG15 mutants to bind USP18 mirrored the gradient pattern of ISG mRNA regulation and corresponding effects on viral infection." (PMID 39931755, 2025). "USP18, STAP1, and OAS3 are involved in anti-viral response and have been shown to be upregulated in blood or lung tissue during viral infection." (PMID 41496780, 2025). "Although most ISGs encode proteins capable of inhibiting different stages of the SARS-CoV-2 replication cycle, a few ISGs, including SOCS, USP18, and IFI44, can promote viral infection of the host." (PMID 36189314, 2022). "Further validation was performed using Nbs1f/f cell lines in which the de-ISGylase, Usp18, was disrupted via CRISPR-Cas9 editing and an exogenous doxycycline inducible 6HIS-ISG15 integrated via lenti-viral infection (Usp18−/−+6his-ISG15)." (PMID 36216822, 2022).
viral infection (continued). "The interaction between USP18 and MAVS is enhanced following viral infection, suggesting the possible regulation of MAVS activity by USP18." (PMID 34016972, 2021). "ISG moieties can reversibly be removed by the deISGylating enzyme UBP43 (USP18), which also acts as an important negative regulator of type I IFN receptor (IFNAR) signaling during viral infection." (PMID 33530371, 2021). "As the major ISG15 de-conjugating enzyme, USP18 is an off-switch in ISGylation, striping ISG15 from its target proteins (known as deISGylation) and playing important role in viral infections through its ISG15 protease activity." (PMID 32248821, 2020). "In other contexts, such as upon viral infection or oxidative stress, ISG15 and USP18 can reach high levels." (PMID 30858391, 2019). "We found that USP18, which is induced by IFN-α/-β in response to viral infection, is also expressed in tumor cells after endogenous and exogenous type-II IFN-γ signaling activation." (PMID 24884733, 2014). "Originally, USP18 is identified as a deISGlase, which specifically cleaves the small ubiquitin-like ISG15 from ISGlated proteins to dampen the interferon-induced overwhelmed response to viral infections." (PMID 38779488, 2024). "USP18 upregulated the IFN production and expression following virus infection." (PMID 35795789, 2022). "USP18-knockout mice experienced pronounced increases in protein ISGylation and were resistant to infection by lymphocytic choriomeningitis virus (LCMV), VSV, Sindbis virus, HIV, and other viral infection involving the ISGylation process." (PMID 31871427, 2019). "Previous studies demonstrated that USP18 can be induced by viral infections and IFN treatment, suggesting that USP18 may play a critical role in inflammation and host innate immune response." (PMID 29285303, 2017). "In response to various cellular stresses, particularly viral infections and other immune stimuli, ISG15 conjugation (ISGylation) is mediated by the consecutive action of a three-step catalytic cascade in a similar manner to ubiquitylation, and conversely counteracted by USP18 isopeptidase activity." (PMID 39843430, 2025). "Taken together, these data illustrate that the effects of USP18 in any given viral infection can be mediated by a number of routes and may or may not be dependent on the USP18 deconjugase function or on a direct inhibition of IFN signaling." (PMID 31871427, 2019). "USP18, a member of the ubiquitin-specific proteases family of enzymes cleaving ubiquitin from ubiquitinated protein substrates, is an INF-stimulated gene 15-specific protease functioning as a negative regulator of IFN α/β signaling pathway and is specifically induced by viral infection and IFNα/β." (PMID 29416786, 2018). "Thus, developing an inhibitor that selectively targets USP18 catalytic activity might represent a novel pharmaceutical approach to enhance resistance to viral infections without side effects or affecting the protease-independent functions of USP18." (PMID 30126853, 2018).
lung carcinoma (16 papers, 2017 to 2025). "Given that 14-3-3ζ levels were associated with USP18 expression, it was explored if USP18 expression affected lung cancer migration and invasion following induced changes in 14-3-3ζ expression." (PMID 35387560, 2022). "Reverse Phase Protein Arrays (RPPAs) in shRNA knock-down lung cancer cells showed that 14-3-3ζ protein was regulated by loss of USP18." (PMID 35387560, 2022). "This study found that engineered loss of USP18 expression markedly reduced the ability of lung cancer cells to migrate and invade." (PMID 35387560, 2022). "USP18 was revealed to be upregulated in lung cancer, and reduced USP18 expression was found to be associated with significantly longer cancer-specific survival in patients with muscle-invasive bladder cancer." (PMID 33051403, 2020). "There was a significant (P < 0.0001) positive correlation and association between PTEN and USP18 protein expression profiles in human lung cancers." (PMID 27980214, 2017). "As these studies unfold, it is important to keep in mind that engineered loss of USP18 does reduce lung cancer formation in mouse models (19 and L.M. Mustachio personal communication)." (PMID 27980214, 2017). "This study explores if the loss of USP18 reduced lung cancer metastasis." (PMID 35387560, 2022). "It was hypothesized that differential expression of these species accompanied loss of USP18 expression and accompanied the observed reduction of lung cancer cell growth." (PMID 27980214, 2017). "Likewise, engineered loss of USP18 expression decreased lung cancer cell growth and increased apoptosis in these cancer cells [19 and LM Mustachio personal communication]." (PMID 27980214, 2017). "Likewise, genetic loss of USP18 repressed cancer formation in engineered murine lung cancer models." (PMID 35159348, 2022). "Notably, loss of Usp18 in KrasLA2/+ mice has been reported to significantly attenuate lung cancer formation, compared to parental KrasLA2/+ mice harboring activated KRAS, pinpointing the implication of USP18 as a potential therapeutic target for cancer treatment." (PMID 32957626, 2020). "A small number of cell lines, A549, H358, H2030, and H1650 lung cancer lines were selected and first evaluated for their USP18 expression." (PMID 39843430, 2025). "The expression of USP18 has been shown to be deregulated in lung cancer, breast cancer, bladder cancer, hepatocellular carcinoma and melanoma." (PMID 40374599, 2025). "We further utilized them for profiling the USP18 activity in cell lines derived from lung carcinoma." (PMID 39843430, 2025). "Engineered reduced USP18 expression in the indicated lung cancer cell lines inhibited the ability of lung cancer cells to migrate and invade." (PMID 35387560, 2022). "USP18 knock-down reduced lung cancer growth, wound-healing, migration, and invasion versus controls (P < .001) and markedly decreased murine lung cancer metastases (P < .001)." (PMID 35387560, 2022). "Migration and invasion assays were independently performed on these USP18 knock-down lung cancer cell lines after individual introduction of USP18-targeting siRNAs versus control siRNAs." (PMID 35387560, 2022). "RPPAs revealed that USP18 expression affected 14-3-3ζ protein levels in murine and human lung cancer cells." (PMID 35387560, 2022). "Added evidence came from interrogating 14-3-3ζ immunohistochemical expression profiles in primary versus metastatic lung cancers after USP18 knock-down versus controls." (PMID 35387560, 2022). "The second lung cancer metastasis model used tail vein injection of USP18 knock-down transfectants achieved by independent introduction of different siRNAs into the 344SQ murine lung cancer cell line." (PMID 35387560, 2022). "USP18 knock-down in lung cancer cells was independently achieved using small hairpin RNAs (shRNAs) and small interfering RNAs (siRNAs)." (PMID 35387560, 2022). "Taken together, these data implicate USP18 as a therapeutic target for reducing lung cancer metastasis." (PMID 35387560, 2022).